IL17A (interleukin 17A)
Diseases named in the same sentence as IL17A in open-access papers (continued):
Sharing a sentence is not in itself a finding about the gene and the disease.
celiac disease (20 papers, 2013 to 2026). An autoimmune genetic disorder with an unknown pattern of inheritance that primarily affects the digestive tract. "Two in vitro models for human intestinal epithelium, small intestinal enteroids and polarized tight monolayers, were utilized to assess how interferon-γ, interleukin-17A, celiac disease-associated bacteria and gluten influence intestinal epithelial cells." (PMID 28934294, 2017). "Our aim in this study was to determine soluble tumor necrosis factor (TNF)-like weak inducer of apoptosis (sTWEAK) and interleukin-17A (IL-17A) levels in celiac disease, and their association with the gluten diet and autoantibodies." (PMID 27367991, 2016). "In addition to innate protective effects, Th17 cells are implicated in celiac disease pathogenesis, where gluten and bacteria trigger IL-17A responses in the intestinal mucosa, and are also associated with villus atrophy." (PMID 39300663, 2024). "All of these results show that the increasing IL-17A level could be associated with the pathogenesis of celiac disease, which is an autoimmune/chronic disease." (PMID 27367991, 2016). "If we could attain data on the autoantibody levels of the control group, we could determine whether sTWEAK and IL-17A are independent risk factors for celiac disease." (PMID 27367991, 2016). "Previous studies have shown that IL-17A and IL-18 are elevated in the serum and intestinal mucosa of celiac disease patients, and correlate with the severity of villous atrophy and inflammation." (PMID 38756445, 2024). "An increased level of interleukin-17A and interleukin-18 in the serum and intestinal mucosa of celiac disease patients reflecting the severity of villous atrophy and inflammation was documented." (PMID 38756445, 2024). "We found, as in celiac disease, strong upregulation of IL-17 signaling and Th17 cell differentiation in EED including induction of IL21, IL6, IL17A IL17F, IL22, IFNG, IL21R, and IL2RA." (PMID 39300663, 2024). "In celiac disease, the sTWEAK and IL-17A levels differ between patients who cannot adapt to the gluten diet and who are autoantibody positive, and patients who adapt to the diet and are autoantibody negative." (PMID 27367991, 2016). "Frequencies of IL-17A+ lymphocytes are higher in small intestinal biopsies of patients with untreated celiac disease (Untreated CD) compared to controls both within the epithelium and in the lamina propria." (PMID 23326425, 2013). "Ability of IFN-γ and IL-17A to significantly upregulate mRNA levels of 38 genes that are expressed at increased levels in IECs of patients with active celiac disease as determined by qRT-PCR in the T84 polarized tight monolayer and the enteroid in vitro models." (PMID 28934294, 2017). "Because, in order to understand the presence of cytokines such as IL-17-A/sTWEAK in the inflammation pathogenesis of the celiac disease, different levels of cytokines, other than the control group, and their determinations as predictors of the disease are precious." (PMID 27367991, 2016). "Consequently, sTWEAK and IL-17A levels were found to be different from the control group for celiac disease." (PMID 27367991, 2016). "In this study, the salivary levels of interleukin-17A, interleukin-1beta, and interleukin-18 in 23 celiac disease patients on a gluten-free diet were evaluated against 23 non-celiac controls." (PMID 38756445, 2024). "Although the present enteritis model does not simulate the pathophysiology of clinical GI disorders such as celiac disease, IBD and IBS, our findings may provide a novel point of view for evaluating the role of T cells and IL-17A in GI disorders." (PMID 24796324, 2014). "A dense infiltrate of IL-6+ mononuclear cells was detected in active coeliac disease, also localised to the upper lamina propria, with significantly increased mRNA expression of IL-6 and IL-17A but not IL-23 p19." (PMID 25198673, 2014).
celiac disease (continued). "IL-17A, IFN-γ and Foxp3 mRNA levels correlate in small intestinal mucosa of patients with untreated celiac disease (Untreated CD) but not in symptom-free celiac disease patients on gluten-free diet (Treated CD)." (PMID 23326425, 2013).
encephalitis (19 papers, 2012 to 2026). An acute inflammatory process affecting the brain parenchyma. "Four studies reported the CSF concentration of IL-17 or IL-17A for encephalitis patients (n = 90) and control group (n = 90)." (PMID 36048783, 2022). "Concentrations of IL‐1β, IL‐6, and IL‐17A dramatically increased in anti‐NMDAR encephalitis group compared with controls (p < 0.0001)." (PMID 31313506, 2019). "The present study shows that the concentration of CSF IL-17A was increased in non-NMDAR cell surface Ab encephalitis and that this increase was associated with disease severity at onset." (PMID 34054854, 2021). "Thus, IL-17A/IL-6 co-activation in anti-NMDAR encephalitis may be a key factor in the pathogenesis of the disease and the production of intrathecal antibodies." (PMID 35937071, 2022). "Compared with peak EAE, WNV encephalitis and ECM in C57Bl/6 WT mice CNS Il17a expression was significantly higher in the GF/IL17A mice (peak EAE: 10.6 ± 1.8, WNV 7.8 ± 4.6, ECM: 8.8 ± 5.1, for all p < 0.0001 compared to GF/IL17 mice)." (PMID 23468966, 2013). "Various inflammatory cytokines/chemokines, such as IL-6, IL-17A, CXCL13 in cerebrospinal fluid, and IL-2 in plasma, and miRNAs (like e.g., Let-7b) in plasma, have been shown to play important roles in the process of anti-NMDAR encephalitis." (PMID 40948637, 2025). "Several studies have shown that IL-6 is elevated in the CSF of patients with anti-NMDAR encephalitis but not in anti-LGI1 encephalitis, often accompanied by increased IL-17A and CXCL13, suggesting a subtype-specific pattern of Th17-driven inflammation." (PMID 41041342, 2025). "IL-4 CCL11, CCL17, CCL21), Th17 (IL-17A, GM-CSF), B cell molecules (BAFF, APRIL) and other cytokine/chemokines including IL-21, IL-1b, IL-12p40, CCL2 and IL-12p70 were detected in less than 50% of patients with encephalitis." (PMID 27575749, 2016).
pulmonary hypertension (19 papers, 2013 to 2025). Increased pressure within the pulmonary circulation due to lung or heart disorder. "Furthermore, researchers have found that the level of Th17 cells and interleukin-17A (IL-17A) increased in PH patients associated with connective tissue disease and idiopathic pulmonary hypertension (IPH), which suggested that Th17 cells may play a crucial role in promoting the development of PH." (PMID 31737467, 2019). "Our data suggest that IL-17A blockade could represent a novel therapeutic approach for PGD after transplantation but perhaps also in other detrimental conditions such as pulmonary embolism, ARDS or pulmonary hypertension." (PMID 23936171, 2013).
vasculitis (19 papers, 2012 to 2025). "From large to small vasculitis, histopathological lesions are different but evidence hints that T-helper (Th)-17 cells and IL-17A are involved in their pathogenesis." (PMID 35479069, 2022). "Regarding IL-17A effects on the CV system, this cytokine could play a role in vasculitis pathogenesis which is characterized by blood vessel wall inflammation, endothelial injury and tissue damage." (PMID 35479069, 2022).
visceral leishmaniasis (19 papers, 2012 to 2025). A severe form of leishmaniasis characterized by irregular bouts of fever, substantial weight loss, swelling of the spleen and liver, and anemia (which may be serious). "In asymptomatic individuals and VL patients after treatment, MAIT cells also produced IL-17A, a cytokine signature associated with resistance to visceral leishmaniasis, suggesting that MAIT cells play important role in protecting against VL." (PMID 36189274, 2022). "In contrast, in symptomatic cases coinfected with HIV and kala-azar, elevated serum levels of IL-6, IL-10, and IL-17A were identified compared to healthy and asymptomatic controls." (PMID 41003560, 2025). "In Sudan, individuals with kala-azar have high levels of IFN-γ, TNF-α, IL-4, IL-6, IL-10, IL-12, and IL-17A." (PMID 41003560, 2025).
aspergillosis (18 papers, 2013 to 2025). Aspergillosis is an infection, growth, or allergic response caused by the Aspergillus fungus. "Vγ1 γδ T cells were reported as an IL-17A-producing cell in certain circumstances, such as in the lethal pulmonary aspergillosis infections." (PMID 35017553, 2022). "We also measured IL-12/23 (the p40 subunit) and IL-17A, cytokines relevant for driving Th responses in aspergillosis." (PMID 30687649, 2018). "Some studies, on the contrary, provide evidence that outcome of aspergillosis in human is independent of TH17 responses, and the IL-23/IL-17A–driven inflammation could impede antifungal immune resistance and promote infection of A. fumigatus." (PMID 30409128, 2018).
autoimmune myocarditis (18 papers, 2010 to 2025). Autoimmune myocarditis is an autoimmune disease that affects the heart. "A study indicated that the extent of myocardium injury is ameliorated by the IL-17A neutralizing antibody in the autoimmune myocarditis model." (PMID 23977238, 2013). "IL-17A expression was markedly increased in hearts of mice with autoimmune myocarditis." (PMID 39502194, 2024).
cryptococcal infection (18 papers, 2011 to 2025). "After cryptococcal infection, γδ T cells secrete IL-17A and interferon gamma (IFN-γ) in mature neutrophils." (PMID 37251371, 2023). "It was recently reported that a type I IFN induction via poly-ICLC protected mice against cryptococcosis and that the protective effect was diminished by the neutralization of IL-17A, demonstrating the protective function of IL-17A." (PMID 36294634, 2022). "Mice deficient in γδ T cells have improved infectious outcomes after C. neoformans challenge, but studies in a protective model of cryptococcosis suggest that γδ T cells are a source of beneficial IL-17A in the setting of neutropenia." (PMID 28936464, 2017). "In the next experiment, we examined how the deficiency of type I-IFN signaling affected the Th17 response to cryptococcal infection by measuring the production of IL-17A and IL-23p19 in the lungs." (PMID 26384031, 2015). "In our model of protection against pulmonary cryptococcosis using C. neoformans strain H99γ, IL-17A production appears to work in concert with Th1-type immune responses to mediate protection and prevent dissemination to the brain." (PMID 23216912, 2012). "Elevated IL-17A production in the lungs correlates with protective immune responses against cryptococcal infection and resolution of infection." (PMID 21359196, 2011). "Altogether, our results suggested that IL-17A may be important for optimal protective immune responsiveness during pulmonary C. neoformans infection, but protective Th1-type immune responses are sufficient for protection against cryptococcal infection." (PMID 21359196, 2011). "In a protective model of cryptococcosis, neutrophils are the primary source of IL-17A that enhances protective immune responses, although they are not essential as γδ T cells can produce IL-17A in their absence." (PMID 28936464, 2017). "In contrast, administration of recombinant IFN-αA/D significantly suppressed the production of IL-4, but not of IFN-γ and IL-17A, in the lungs of WT mice after cryptococcal infection." (PMID 26384031, 2015). "In the current study, the production of IL-17A and IL-23p19 in the lungs was higher in IFNAR1KO mice than in WT mice after cryptococcal infection, suggesting that the promoted Th17 and neutrophilic response may account for the increased host resistance to cryptococcal infection in IFNAR1KO mice." (PMID 26384031, 2015). "Furthermore, the IL-17A produced in our model of cryptococcal infection was not proceeded or accompanied by the production of cytokines that typically initiate Th17-type responses (i.e., TGF-β, IL-21, or IL-23)." (PMID 23216912, 2012). "In this study, IFN-I was identified as the early response cytokine to Cryptococcus neoformans infection via quantitative PCR (qPCR) and IFN-I was demonstrated to be crucial for interleukin (IL)-17A secretion in T cells, but not in innate immune cells." (PMID 24660033, 2014).
cutaneous leishmaniasis (18 papers, 2011 to 2026). Leishmaniasis affecting the skin. "IL-17A has been implicated in the immunopathology of several experimental models of cutaneous leishmaniasis." (PMID 34699567, 2021). "An increase in IL-17A after PBMC stimulation has been also described in cutaneous leishmaniasis caused by L. (L.)braziliensis." (PMID 28747911, 2017). "Thus, we identify a pathogenic role for IL-17A in LRV1-dependent cutaneous leishmaniasis and infectious metastasis." (PMID 27658195, 2016). "IL-17A-producing RORγt+ ILCs along with skin microbiota alterations contribute to the pathology of cutaneous leishmaniasis." (PMID 38396697, 2024). "Taken together, this study indicates that the skin microbiota promotes RORγt+ IL-17A-producing ILCs, which augment the skin inflammation in cutaneous leishmaniasis." (PMID 34699567, 2021). "Here we show the involvement of IL-17A-producing ILCs in microbiota-driven immunopathology in cutaneous leishmaniasis." (PMID 34699567, 2021). "Using a combination of murine models and human studies we and others have shown that the skin microbiome enhances IL-1β and IL-17A production and contributes to increased pathology in cutaneous leishmaniasis." (PMID 34699567, 2021). "We extend the current understanding of immunopathology in cutaneous leishmaniasis by demonstrating that commensal microbiota induced IL-17A-producing RORγt+ ILCs drive the early pathology in L. major infected mice via recruitment of neutrophils to the site of infection." (PMID 34699567, 2021). "Notably, blockade of IL-17A in Rag1-/- mice colonized with S. epidermidis before L. major infection significantly reduced the inflammation suggesting that IL-17 production from ILCs is sufficient to drive inflammation in acute phase of cutaneous leishmaniasis." (PMID 34699567, 2021).
esophageal squamous cell carcinoma (18 papers, 2011 to 2024). Esophageal squamous cell carcinoma (ESCC) is a type of esophageal carcinoma (EC) that can affect any part of the esophagus, but is usually located in the upper or middle third. "Although studies have shown that IL-17A can promote the migration and invasion of EAC cells (esophageal squamous cell carcinoma) through ROS/NF-κB/MMP-2/9 signaling pathway activation." (PMID 39906741, 2024). "However, in esophageal squamous cell carcinoma (ESCC), IL-17A overexpression significantly correlated with improved 1-year (OR = 0.34, 95% CI 0.19 to 0.60, P = 0.000), 3-year (OR = 0.48, 95% CI 0.32 to 0.73, P = 0.000) and 5-year OS (OR = 0.53, 95% CI 0.35 to 0.80, P = 0.002)." (PMID 29029520, 2017).
ZIKV infection (18 papers, 2017 to 2025). "The systemic inflammatory response during the acute stage of Zika fever is characterized by high circulating levels of the cytokines and chemokines IL-9, IL-17A, and CXCL10." (PMID 33430059, 2021). "We do not know whether lower levels of IL-1β, IL-6, IL-8, IL-10, IL-12, IL-13, IL-17A, TNF, and IFN-γ in ZIKV offspring at 32 days were caused by subclinical in utero ZIKV infection or maternal cytokine background." (PMID 31725819, 2019). "Previous ZIKV infection could lead to development of low-affinity cross-reactive immunological memory against epitopes in DENV, which would lead to pathogenic T helper cell responses in a subsequent infection, in this case, characterized by IL-17A production." (PMID 37943879, 2023). "The samples from pregnant women with ZIKV infection included in this study showed increases in all anti-inflammatory cytokines (IL-10), and some pro-inflammatory cytokines (IL-6, IFN-γ, IFN-α, and IL-17A), chemokines (CXCL10, CCL2, CXCL9, and CXCL8), and receptors (IL-1RA and IL-2R)." (PMID 33430059, 2021). "Our results further suggest that IL-17A, but not IL-17F, specifically inhibits the expression of IFN-α2 during CHIKV, but not WNV or ZIKV infection." (PMID 33304351, 2020). "However, surprisingly, we detected an increase in IL-17A+ IFN-γ+-producing CD4+ T cells (Th1Th17 cells) in the mothers and children, but not in the women with a history of ZIKV infection." (PMID 35215843, 2022). "Interestingly, the results suggested that IL-17A has no such effect on IFN-α2 production during WNV and ZIKV infections." (PMID 33304351, 2020). "Interestingly, depletion of CD14+ monocytes and ZIKV infection did not affect the levels of epidermal growth factor (EGF), interleukin 9 (IL-9), IL-17A, macrophage inflammatory protein 1α (MIP-1α), and MIP-1β." (PMID 29600283, 2018).
alopecia areata (17 papers, 2018 to 2025). Loss of scalp and body hair involving microscopically inflammatory patchy areas. "The underlying mechanism of alopecia areata upon IL-17A inhibitor exposure remains to be elucidated." (PMID 41306762, 2025). "Moreover, the pathogenesis of alopecia areata is believed to involve inflammatory cytokines IL-17A and monoclonal antibodies against IL-17A secukinumab-caused hair regrowth in human volunteers." (PMID 30208587, 2018). "IL-17A: interleukin 17A; IL-23: interleukin 23; n: number; *Significant, Group A: diagnosed patients with alopecia areata; Group B: apparently healthy individuals." (PMID 41583149, 2025). "It found that people with alopecia areata had increased plasma levels of the Type 2 cytokines IL-33, IL-31 and IL-17E (IL-25), in addition to the Type 17 cytokines IL-17A, IL-21, IL-23 and IL-17F." (PMID 38892934, 2024). "Similarly, the concentration of serum IL-17A, a proinflammatory cytokine characteristic of the Th17 subset, has been determined to be markedly higher in individuals suffering from alopecia areata." (PMID 40352276, 2025). "The mean serum levels of IL-6, TNF-α, IL-17A, and IL-21 were comparable between the two sexes, with p values exceeding 0.05, indicating that gender did not appear to influence the systemic inflammatory response in alopecia areata." (PMID 41002719, 2025). "This systematic review and meta-analysis were done to find the association between rs3118470, rs2275913, rs3212227, and rs10889677 of the IL2RA, IL17A, IL12B, and IL23R genes, respectively, of the interleukin family with alopecia areata." (PMID 38394507, 2024). "Throughout the assessment, 165 articles were not related to Alopecia Areata and IL2RA, IL17A, IL12B IL23R genes, 11 were non-English publications and 5 articles were on animal models." (PMID 38394507, 2024).
autism spectrum disorder (17 papers, 2012 to 2025). A spectrum of developmental disorders that includes autism, and Asperger syndrome. "Most recently, IL-17a, a downstream product of IL-6, from a subset of T helper cells was found to cause cortical defects and is associated with autism-spectrum disorder behavior in offsprings, providing relevance to the finding that the mother’s immune system during pregnancy impacts fetal outcome." (PMID 40710297, 2025). "In this review, we examined the signaling pathways in both immunological and neurological contexts that may contribute to the improvement of autism spectrum disorder symptoms associated with maternal blocking of interleukin-17A and adult exposure to interleukin-17A." (PMID 35211045, 2022).